GABPB1 (GA binding protein transcription factor subunit beta 1)
Description:
Transcription factor capable of interacting with purine rich repeats (GA repeats). Acts as a master regulator of nuclear-encoded mitochondrial genes (By similarity). (Microbial infection) Necessary for the expression of the Adenovirus E4 gene.
Synonyms: GABPB-1; E4TF1B; GABPB; GABPB2; E4TF1-47; BABPB2; E4TF1; E4TF1-53; NRF2B1; NRF2B2
Tractability: PROTAC: ubiquitination databases record sites on it; its protein half-life has been measured.
Gene: Protein-coding gene on chromosome 15 (50,275,389 to 50,355,440, reverse strand). Ensembl gene ENSG00000104064.
Subcellular location: Nucleus
Subcellular location (Human Protein Atlas): Nucleoplasm; Cytoplasmic bodies
Pathways (Reactome):
Organelle biogenesis and maintenance: Transcriptional activation of mitochondrial biogenesis
Gene Ontology:
Molecular function: protein binding; transcription cis-regulatory region binding
Biological process: positive regulation of transcription by RNA polymerase II; mitochondrion organization
Cellular component: nucleoplasm; nucleus
Genetic constraint (gnomAD): Loss-of-function variants: 13 observed, 34.54 expected, observed/expected ratio (o/e) 0.38, 90% interval 0.24 to 0.6. The upper end of that interval is the gene's LOEUF score, 0.6, which puts it in group 2 of 6, group 1 being the genes least tolerant of losing a copy. Missense variants: 198 observed, 375.63 expected, observed/expected ratio (o/e) 0.53, 90% interval 0.47 to 0.59. Synonymous variants: 108 observed, 124.07 expected, observed/expected ratio (o/e) 0.87, 90% interval 0.74 to 1.02.
Homologues: Orthologues: dog GABPB1 (100% identical), macaque GABPB1 (100% identical), rabbit GABPB1 (100% identical), mouse Gabpb1 (98% identical), tropical clawed frog gabpb1 (96% identical), pig GABPB1 (87% identical), rat Gabpb1 (87% identical), chimpanzee GABPB1 (80% identical), guinea pig GABPB1 (79% identical), rat Gabpb1l (77% identical), zebrafish gabpb1 (65% identical). Paralogues in human: GABPB2 (70% identical), IQANK1 (19% identical).
Diseases named in the same sentence as GABPB1 in open-access papers:
GABPB1 is named in the same sentence as 33 diseases in open-access papers, as found by Europe PMC text mining. Sharing a sentence is not in itself a finding about the gene and the disease. The quoted sentences say what the papers report.
glioblastoma (9 papers, 2019 to 2023). The most malignant astrocytic tumor (WHO grade IV). "Indeed, glioblastoma cells knocked-out of GABPB1, the GABPA partner required for activation of the mutated TERT promoter, was shown to undergo telomere shortening, senescence or apoptosis and eventual loss of tumorigenesis." (PMID 35549739, 2022). "In glioblastoma cells harboring the TERT promoter mutation, GABPB1 depletion led to reduced TERT expression coupled with diminished telomerase activity followed by progressive telomere attrition and eventual loss of oncogenic potential." (PMID 35549739, 2022). "More importantly, GABPB1 knockout inhibits TERT expression and telomerase activity in TERT promoter-mutated glioblastoma cells, disrupting telomere length maintenance through which apoptosis is induced." (PMID 35326537, 2022). "TERT promoter mutations occur in the majority of glioblastoma, bladder cancer (BC), and other malignancies while the ETS family transcription factors GABPA and its partner GABPB1 activate the mutant TERT promoter and telomerase in these tumors." (PMID 31802036, 2020). "GABPA depletion or the disruption of the GABPA/GABPB1 complex by knocking down GABPB1 was shown to inhibit telomerase, thereby eliminating the tumorigenic potential of glioblastoma cells." (PMID 31802036, 2020). "Indeed, following stable GABPB1 knockdown, glioblastoma cells carrying C228T or C250T TERT promoters undergo diminished TERT/telomerase expression, progressive telomere erosion and eventual loss of tumorigenic potential." (PMID 36713366, 2022). "Since the long variant of GABPB1 mRNA (GABPB1L) but not its shorter transcripts was observed to play a functional role in the activation of the mutated TERT promoter in glioblastoma, we further determined GABPB1L expression in the same tumors." (PMID 35326537, 2022). "GBMs decreases GABPB1 and GABPB1L mRNA levels and it could be used as a potential therapeutical approach together with targeting therapy in TERT and GABP dependent glioblastomas." (PMID 34194624, 2021). "Between primary and secondary glioblastomas with and without chemotherapy, TERT is elevated in the former while GABPB1 is increased in the secondary glioblastomas." (PMID 34194624, 2021). "In secondary glioblastomas after chemotherapy, GABPB1 and GABPB1-L are expressed on a lower level than without treatment." (PMID 34194624, 2021).
glioma (3 papers, 2019 to 2025). A benign or malignant brain and spinal cord tumor that arises from glial cells (astrocytes, oligodendrocytes, ependymal cells). "In grade III gliomas, GABPB1 negative correlates with TERT significantly (r = −0.65, 95% CI = −0.85–0.27; p = 0.003)." (PMID 34194624, 2021). "As a result, GABPB1 is now considered a promising target for inhibiting TERT and treating gliomas without toxicity." (PMID 40463649, 2025).
lung carcinoma (3 papers, 2023 to 2024). "Low levels of HOMER3 or GABPB1 cause severe mitochondrial dysfunction, thereby inhibiting the growth and metastasis of lung cancer." (PMID 38081871, 2023). "In parallel, experiments were conducted using short hairpin RNA (shRNA) to suppress the GABPB1 gene in human lung cancer cells to evaluate the effects on cell proliferation, viability, and apoptosis." (PMID 38466508, 2024). "In this study, we utilized database information to observe the expression of GABPB1 in lung cancer and its relationship with clinical characteristics and prognosis, as well as its impact on tumor immunity." (PMID 38466508, 2024). "We tested paired lung cancer tissue and normal tissue after surgery and found that GABPB1 was expressed in multiple cells." (PMID 38466508, 2024). "Mechanistically, the binding of HOMER3 and PAFAH1B3 activates the transcriptional regulation of mitochondrial genes by GABPB1 in lung cancer cells." (PMID 38081871, 2023). "Apoptosis in lung cancer cells following GABPB1 knockdown was evaluated using flow cytometry." (PMID 38466508, 2024). "By identifying the predominant population affected by GAPBP1-targeted therapy and determining the prognosis of lung cancer patients, we hope to find additional evidence to support the clinical application of GABPB1 in the diagnosis and treatment of lung cancer." (PMID 38466508, 2024). "Taken together, as a transcription factor, GABPB1 influences the development of lung cancer through various mechanisms, and the specific role of GABPB1 may vary in different types of cancer, which results in different prognostic impacts." (PMID 38466508, 2024). "We tested samples from lung cancer patients who underwent standard surgery, and the results showed that GABPB1 was expressed in alveolar epithelial cells, vascular endothelial cells, and lung cancer cells and was localized in both the nucleoplasm and cytoplasmic bodies." (PMID 38466508, 2024). "Therefore, we believe that HOMER3 controls the tumorigenic potential of lung cancer by regulating the GABPB1-dependent mitochondrial Asp synthesis." (PMID 38081871, 2023). "We also determined whether the GABPB1-induced changes in mitochondrial inner membrane genes affect the mitochondrial function of lung cancer cells by measuring both the OCR and ECAR." (PMID 38081871, 2023). "Moreover, overexpression of GABPB1 also partially reversed the decrease of invasive ability and lung metastasis of lung cancer cells induced by HOMER3 knockdown." (PMID 38081871, 2023). "Furthermore, additional supplementation with Asp was found to reverse the GABPB1 knockdown-induced decreased proliferation of lung cancer." (PMID 38081871, 2023). "However, the role and mode of action of GABPB1 in malignant tumors, especially in lung cancer, are not well understood and need further research." (PMID 38466508, 2024). "However, the relationship between GABPB1 and malignant tumors, especially lung cancer, has largely not been determined." (PMID 38466508, 2024). "However, the role of GABPB1 in malignant tumors, especially lung cancer, has not been fully elucidated, and the relevant mechanisms also need to be further explored." (PMID 38466508, 2024). "However, we found that while GABPB1 deletion reduced the OCR of lung cancer cells, it did not significantly affect ATP production." (PMID 38081871, 2023).
melanoma (3 papers, 2019 to 2024). A malignant, usually aggressive tumor composed of atypical, neoplastic melanocytes. "In the present study, we showed that TRPM7, SPPL2A, and GABPB1 are involved in the proliferation of canine and human non-UV-induced melanomas." (PMID 35053440, 2022).
thyroid cancer (3 papers, 2022 to 2023). "Similarly, GABPB1 downregulation due to the gene hypermethylation is observed in thyroid carcinoma and its inhibition promotes invasion of thyroid cancer cells, too." (PMID 35549739, 2022). "Based on our pan-cancer analysis, the hypermethylation of cg14821257 of the GABPB1 gene may have a unique functional role to be further uncovered within thyroid cancer." (PMID 35326537, 2022).
hepatocellular carcinoma (2 papers, 2021 to 2024). A malignant tumor that arises from hepatocytes. "GABPB1, has been associated with ferroptosis and can be used as a therapeutic target in hepatocellular carcinoma." (PMID 34338139, 2021). "In patients with hepatocellular carcinoma (HCC), high expression of GABPB1 has been shown to correlate positively with poor prognosis." (PMID 38466508, 2024).
lung adenocarcinoma (2 papers, 2022 to 2024). A carcinoma that arises from the lung and is characterized by the presence of malignant glandular epithelial cells. "However, in both lung adenocarcinoma and lung squamous cell carcinoma, methylation alters the original association of GABPB1 with infiltrating tumor immune cells." (PMID 38466508, 2024). "Our in-depth database investigation revealed that GABPB1 expression is related to the immune subtypes of squamous cell carcinoma and adenocarcinoma of the lung." (PMID 38466508, 2024). "We also conducted an analysis of GABPB1 methylation in lung adenocarcinoma and lung squamous cell carcinoma using the TCGA database." (PMID 38466508, 2024). "Overexpression of GABPB1 was observed in both lung adenocarcinoma and lung squamous cell carcinoma." (PMID 38466508, 2024). "Like that of other ETS family factors, the expression of GABPB1 was related to a variety of tumor immune infiltrating cells, and the expression of GABPB1 was consistently correlated with immune-infiltrating cells in both lung adenocarcinoma and squamous cell carcinoma." (PMID 38466508, 2024). "By looking at the average β value across all CpG sites of GABPB1, THCA is ranked second following LUAD (lung adenocarcinoma)." (PMID 35326537, 2022).
non-small cell lung carcinoma (2 papers, 2023 to 2024). A group of at least three distinct histological types of lung cancer, including non-small cell squamous cell carcinoma, adenocarcinoma, and large cell carcinoma. "Our research focused on examining the biological function of GABPB1 in NSCLC (Non-Small Cell Lung Cancer)." (PMID 38466508, 2024).
renal carcinoma (2 papers, 2022 to 2024). A carcinoma arising from the epithelium of the renal parenchyma or the renal pelvis. "Knockdown of GABPB1 in these cells significantly inhibited colony formation, and increased expression of GABPB1 was associated with poorer survival outcomes in patients with renal cancer." (PMID 38466508, 2024). "The higher expression levels of GABPB1 had associated with poor prognostic in renal cancer." (PMID 35941292, 2022).
acral melanoma (1 paper, 2022). "In the Cancer Genome Atlas, we found one case of acral melanoma (TCGA-ER-A19T-01) harboring a strong focal amplification on chromosome 15 (orthologous to canine chromosome 30) encompassing the candidate oncogenes SPPL2A, USP8, TRPM7, and GABPB1." (PMID 35053440, 2022).
Cerebral ischemia (1 paper, 2025). Restriction of arterial blood supply to the brain associated with insufficient oxygenation to support the metabolic requirements of the tissue. "Notably, lncRNA FTX inhibits ferroptosis in magnesium-free-induced hippocampal neurons via the miR-142-5p/GABPB1 axis and protects against cerebral ischemia–reperfusion injury by enhancing neuronal proliferation and reducing apoptosis through the miR-186-5p/MDM4 pathway." (PMID 40725099, 2025).
liver cancer (1 paper, 2023). An epithelial or non-epithelial malignant neoplasm that arises from the liver. "Previous studies have indicated that lncRNA GABPB1 and its antisense lncRNA GABPB1-AS1 are specifically induced by erastin to regulate oxidative stress in liver cancer cell ferroptosis." (PMID 37258567, 2023).
lung squamous cell carcinoma (1 paper, 2024). "However, the results showed a difference in GABPB1 methylation only between lung squamous cell carcinoma tissue and normal tissue." (PMID 38466508, 2024).
squamous cell carcinoma (1 paper, 2024). A carcinoma arising from squamous epithelial cells. "Observing OS, PFS and the DDS as indicators, our analysis revealed that high GABPB1 expression was indicative of poor prognosis in adenocarcinoma patients; however, our analysis did not reveal a similar conclusion for squamous cell carcinoma patients." (PMID 38466508, 2024).
uterine cancer (1 paper, 2025). Primary or metastatic malignant neoplasm involving the uterine corpus and/or the cervix.
cancer (15 papers, 2018 to 2025). A tumor composed of atypical neoplastic, often pleomorphic cells that invade other tissues. "Like other tumor suppressors, the aberrant promoter hypermethylation and/or copy number loss contribute to the downregulation of GABPA or GABPB1 in the cancer types above." (PMID 36713366, 2022). "Therefore, telomerase/TERT repression by inhibiting GABPB1 expression was proposed as a therapeutic strategy against cancer carrying a mutated TERT promoter." (PMID 35326537, 2022). "The high expression of GABPB1 in most malignant tumors and its research results in specific tumor types seem to confirm its cancer-promoting effect on malignant tumors." (PMID 38466508, 2024). "GABPB1, the gene that encodes two isoforms of the beta subunit of GABP, has been identified as an oncogene in multiple malignant tumors." (PMID 38466508, 2024). "At the start of the study, we examined the existing data on GABPB1 in the database, and the results revealed that GABPB1 was expressed in various human normal tissues and malignant tumors at both the protein and RNA levels." (PMID 38466508, 2024). "These unprecedented findings suggest that it should be cautious in targeting GABPA or GABPB1 for cancer intervention." (PMID 35549739, 2022). "Collectively, GABPA and GABPB1 functions are context- or cell type-dependent, and caution should be taken to target them for telomerase-based cancer therapy." (PMID 36713366, 2022). "With the observed hypermethylation of GABPB1 in PTC from our TCGA pan-cancer analysis, we then investigated the effects of GABPB1 hypermethylation within PTC." (PMID 35326537, 2022). "Using a pan-cancer approach, the DNA methylation landscape of the GABPB1 locus was characterized in TCGA data sets." (PMID 35326537, 2022). "Given the requirement of GABPA and GABPB1 to activate the mutated TERT promoter, they have been suggested as targets for telomerase-based cancer therapy." (PMID 36713366, 2022). "GABP1, also known as GABPB1, has been implicated in various cancer types, such as non-small cell lung cancer (NSCLC)." (PMID 39473450, 2024). "Therefore, targeting GABPB1 or GABPA for telomerase-based therapy has been suggested as a novel anti-cancer strategy." (PMID 35549739, 2022). "We therefore hypothesized that serum starvation-induced changes in GABPA and GABPB1 could underlie the relationship between cell proliferation and the regulation of TERT, specifically in TERTp-mutant human cancer cells." (PMID 36130485, 2022). "Moreover, FOS inhibitors were recently observed to induce robust apoptosis in cancer cells harboring a mutant TERT promoter by suppressing GABPB1 and TERT expression." (PMID 35326537, 2022). "Evidently, the loss of GABPB1 or GABPA is a more potent cancer-driving force that compensates for the lack of TERT upregulation." (PMID 35326537, 2022). "Therefore, targeting GABPB1 for cancer therapy should be cautious since it may counteract its tumor-suppressive functions." (PMID 35326537, 2022). "Thus, caution is needed if targeting GABPB1 for cancer therapy is considered." (PMID 35326537, 2022). "Therefore, targeting GABPB1 for anti-telomerase cancer therapy may counteract its tumor-suppressive activity, thereby promoting TC progression, which should be considered in the rational development of telomerase-based strategies against cancer." (PMID 35326537, 2022). "By analyzing interactions with the GNPDA1 protein using the STRING database, researchers identified 4 key genes (GABPB1, CDK4, ADNP, and APH1A) that play important roles in cellular processes related to cancer." (PMID 40419932, 2025). "Given that the ETS family transcription factors GABPA and GABPB1 activate the mutant TERT promoter and induce TERT expression for telomerase activation, GABPB1 has been proposed as a cancer therapeutic target to inhibit telomerase." (PMID 35326537, 2022). "With a rank of 28th out of 33 cancer types, THCA is one of the cancer cohorts with the lowest GABPB1 mRNA expression." (PMID 35326537, 2022).
cancer (continued). "GABPB1 is reported to activate TERT gene expression and has been proposed as a cancer therapeutic target." (PMID 35326537, 2022). "Given all the oncogenic effects of TERT, GABPB1 and GABPA-mediated TERT upregulation is expected to promote cancer progression." (PMID 35326537, 2022). "To evaluate the effect of the altered expression of the CFA30 genes on cancer cell proliferation, we assessed the proliferation capability of canine MM cancer cells after silencing TRPM7, SPPL2A, GABPB1, and USP8 genes using colorimetric cell proliferation assays." (PMID 35053440, 2022). "Consistently, inhibiting the expression of GABPA or GABPB1 rather than other ETS members led to diminished TERT expression in cancer cells bearing a mutant TERT promoter." (PMID 31285550, 2019). "However, GABPA and GABPB1 stimulate TERT transcription, but several lines of evidence suggest that they may serve as tumor suppressors in other cancer types regardless the presence or absence of TERT promoter mutations." (PMID 36713366, 2022).